CDKN2A (cyclin dependent kinase inhibitor 2A)
Diseases named in the same sentence as CDKN2A in open-access papers (continued):
Sharing a sentence is not in itself a finding about the gene and the disease.
neck tumors (1 paper, 2015). "It is worth noting that deletion of CDKN2A is a frequent event in heat and neck tumors." (PMID 26634163, 2015).
odontogenic cyst (1 paper, 2021). A cyst in the jaw that arises from tissues of tooth development.
opisthorchiasis (1 paper, 2024). Infection with flukes of the genus Opisthorchis. "For example, p16, encoded by p16INK4A (CDKN2A), is an inhibitor of CDK4, and the expressions of cyclin D1 and CDK4 are up-regulated in opisthorchiasis-associated CCA." (PMID 39236081, 2024).
parasitic infection (1 paper, 2021). "In addition, the current study specifically characterizes the relationship among TL, CDKN2A, inflammation, oxidative stress and tissue injury, prior, during and post low parasitic infection." (PMID 34548530, 2021).
pharyngeal cancer (1 paper, 2009). "In the study described herein, we tested the association between promoter methylation and survival in a cohort of 88 oral and pharyngeal cancer patients, focusing on three target genes: the DNA repair gene MGMT and the tumor suppressor genes CDKN2A and RASSF1." (PMID 19807915, 2009).
pharyngeal tumors (1 paper, 2009). "We evaluated 88 primary oral and pharyngeal tumors for methylation of the promoter for the DNA repair gene MGMT and the tumor suppressor genes CDKN2A and RASSF1 using methylation-specific PCR." (PMID 19807915, 2009). "The promoter methylation status of the DNA repair gene MGMT and the tumor suppressor genes CDKN2A and RASSF1 were evaluated by methylation-specific PCR in 88 primary oral and pharyngeal tumors and correlated with survival and tumor recurrence." (PMID 19807915, 2009).
phyllodes tumor (1 paper, 2013). A benign, borderline, or malignant fibroepithelial neoplasm arising from the breast and rarely the prostate gland. "Other genetic abnormalities in phyllodes tumor that have been described in the COSMIC database (as of February 2013) are CDKN2A mutation (1/25 ptes), KIT mutation (1/26 ptes), and PI3KCA mutation (1/1 pte)." (PMID 23895135, 2013).
pilomyxoid astrocytoma (1 paper, 2020). An astrocytic tumor of uncertain relation to pilocytic astrocytoma. "CDKN2A deletion status was conserved in 10 (52%) patients with pilocytic or pilomyxoid astrocytomas, with four remaining positive and six remaining negative." (PMID 33153497, 2020).
preeclampsia (1 paper, 2022). Preeclampsia is a hypertensive disorder of pregnancy that is characterized by new-onset hypertension with proteinuria presenting after 20 weeks of gestation, and depending on mild or severe forms may initially present with severe headache, visual disturbances, and hyperreflexia. "Our results indicate that CDKN2A and TXNRD1 are highly expressed in STB-EVs derived from preeclampsia, further studies are needed to identify the impact of CDKN2A and TXNRD1 on ferroptosis pathway." (PMID 36343018, 2022). "ALB, NOX4 and CAV1 are associate with the prosses of preeclampsia, and the other two genes (CDKN2A, TXNRD1) have not been linked directly to the occurrence of preeclampsia." (PMID 36343018, 2022). "In this study, we identified several central genes closely related to ferroptosis in STB-EVs (ALB, NOX4, CDKN2A, TXNRD1, and CAV1) that are potential biomarkers related to ferroptosis in preeclampsia." (PMID 36343018, 2022). "In this investigation, we demonstrated numerous key genes (ALB, NOX4, CDKN2A, TXNRD1, and CAV1) that are expected to act as biomarkers for ferroptosis in STB-EVs of preeclampsia." (PMID 36343018, 2022).
primary effusion lymphoma (1 paper, 2021). A large B-cell lymphoma located in the body cavities, characterized by pleural, peritoneal, and pericardial fluid lymphomatous effusions and that is always associated with human herpes virus-8 (HHV-8). "Transcription repression via CpG DNA hyper-methylation of p16INK4a (CDKN2A), the TGF-beta type II receptor (TbetaRII, TGFBR2), and PDZ-LIM domain-containing protein 2 (PDLIM2) promoters have been detected in KSHV-infected primary effusion lymphoma (PEL) lines." (PMID 34307191, 2021).
primitive neuroectodermal tumor (1 paper, 2023). A malignant neoplasm that originates in the neuroectoderm.
Psoriasiform dermatitis (1 paper, 2016). A skin abnormality characterized by redness and irritation, with thick, red skin that displays flaky, silver-white patches (scales).
rectal adenocarcinoma (1 paper, 2022).
rectal carcinoid tumors (1 paper, 2015). "We selected the six markers [CDKN2A (p16), IGF2, MLH1, MINT1, MINT2, and MINT31] that were methylated in more than 5% of the rectal carcinoid tumors as CIMP markers." (PMID 26090613, 2015).
retinopathy of prematurity (1 paper, 2024). A bilateral retinopathy characterized by neovascularization, scarring, retinal detachment, and eventually blindness. "They found that a single 5 μg dose of IVT metformin reduced expression of several key SASP genes, such as Il6, Cdkn1a, and Cdkn2a, as well as decreased protein levels of IRE1α and NF-κB, highlighting the potential therapeutic effects of IVT metformin in retinopathy of prematurity." (PMID 39518910, 2024).
serous cystadenocarcinoma (1 paper, 2024). A malignant serous cystic neoplasm usually involving the ovary or the pancreas. "For the TCGA serous cystadenocarcinoma ovarian dataset (n=617), cBioPortal data show that 5.9% of CDKN2A genes and 5.7% of PTEN genes have copy number variations." (PMID 39409874, 2024).
Sjögren’s syndrome (1 paper, 2025). "in Sjögren’s syndrome, BAFF is necessary for B-cell survival and function, whereas CDKN2A regulates the cell cycle in NHL." (PMID 40321894, 2025).
somatotroph tumours (1 paper, 2021). "Corresponding to our data on sporadic somatotroph tumours, this low CDKN2A-ARF RNA expression could also explain the well-described resistance of AIP-FIPA tumours to first-generation somatostatin analogues." (PMID 34588620, 2021).
Splenomegaly (1 paper, 2020). Abnormal increased size of the spleen. "They reported that complete loss of CDKN2A accelerated leukemogenesis in HMGA1 transgenic mice that showed marked splenomegaly and significantly decreased OS compared with HMGA1 transgenic/CDKN2A WT mice." (PMID 32503270, 2020).
squamous non-small cell lung cancer (1 paper, 2023). "Interestingly, a recent study also found that non-squamous non-small cell lung cancer (NSCLC) tumor patients with deletion of 9p21.3, which includes CDKN2A sequence, showed worse clinical outcomes after pembrolizumab (anti-PD-1 therapy)." (PMID 36961395, 2023).
tenosynovial giant cell tumor (1 paper, 2024). A tumor usually arising in the synovium of joints, bursa or tendon sheath. "Downregulation expression of CDKN2A was found only in tenosynovial giant cell tumors (TGCT)." (PMID 38894777, 2024).
tonsil (1 paper, 2023). "In HPV-associated and -unrelated TCGA tonsil cancer data, the tendency for CDKN2A (0% vs. 16.7%, respectively), FGFR3 (6.3% vs. 0%, respectively), and RB1 (9.4% vs. 7.9%, respectively) expression was comparable to that observed in our cohort." (PMID 36979829, 2023).
translocation renal cell carcinoma (1 paper, 2025). "In previous studies involving gene-level copy number analysis, the sole recurrent focal alteration identified in translocation renal cell carcinoma was the homozygous deletion of the CDKN2A/2B locus (9p21.3), occurring in 19.2% of cases." (PMID 40177240, 2025).
tubular carcinomas (1 paper, 2017). "One of the two KRAS-mutated tubular carcinomas harbored CDKN2A/p16 mutations." (PMID 28145465, 2017).
uremia (1 paper, 2022). A clinical syndrome associated with the retention of renal waste products or uremic toxins in the blood. "CDKN2A/p16Ink4a and osteogenesis transcriptional factor Runx2 significantly increased in a rat adenine-induced uremia CKD model." (PMID 35656113, 2022).
urinary tract infection (1 paper, 2024). "In in vitro studies, urinary tract infection induced by Escherichia Coli resulted in increased DNMT1 activity, DNA methylation, and downregulation of the tumor suppressor gene CDKN2A." (PMID 38891848, 2024).
Xeroderma pigmentosum complementation group C (1 paper, 2022). "Genes also involved in NMSCs pathogenesis are melanocortin-1 receptor (MC1R), xeroderma pigmentosum complementation group C (XPC), cytochrome P450 2D6 (CYP2D6), cyclin dependent kinase inhibitor 2A (CDKN2A), glutathione S-transferase theta 1 gene (GSTT1), and telomerase." (PMID 36291078, 2022).
yolk sac tumor (1 paper, 2010). A non-seminomatous malignant germ cell tumor composed of primitive germ cells. "In addition, both LOHs of the CDKN2A were found in nonseminomas with a yolk sac tumor component." (PMID 22933911, 2010).
tumor (3,318 papers, 1996 to 2026). "Consistently, immune infiltration analysis revealed striking reductions in various immune cells in KEAP1-, STK11- or CDKN2A-mutated tumors, characterizing the suppressive tumor immune microenvironment (TIME)." (PMID 41491583, 2026). "The poor prognostic value of KEAP1, STK11, and CDKN2A mutations was further validated in the tumor tissue WES/WGS data." (PMID 41491583, 2026). "Abnormal DNA methylation leads to CDKN2A silencing, while histone modification enhances the transcription of pro-inflammatory factors and promotes tumor-associated inflammation." (PMID 41601652, 2026). "Taken together, baseline KEAP1, STK11, and CDKN2A mutations detected by liquid biopsy indicate a poor prognosis, which was also confirmed by tumor tissue-based mutation sequencing data." (PMID 41491583, 2026). "L6565 exhibited homozygous CDKN2A loss with retained Rb expression, rendering tumour cells sensitive to CDK4/CDK6 inhibition via palbociclib." (PMID 41924733, 2026). "WES/WGS and RNA-seq confirmed the poor prognostic effect of KEAP1, STK11, and CDKN2A mutations, which were characterized by the suppressive tumor microenvironment and attenuated humoral immunity." (PMID 41491583, 2026). "In turn, the loss of function of suppressor genes such as PTEN or CDKN2A/B promotes uncontrolled cell growth and tumor progression." (PMID 41465586, 2025). "In conclusion, our data show that in DPM, the deletion of CDKN2A is associated with a significant depletion of stimulatory and chemotactic signals, resulting in the exclusion of immune infiltrate from tumor parenchyma." (PMID 40877968, 2025). "CDKN2A/B homozygous deletion promotes malignant tumor behavior by causing cell cycle disorder and increasing cell proliferation." (PMID 41201287, 2025). "This suggests that the prognosis of the tumor was likely to be associated with positive surgical margins and genomic co-alterations such as CDKN2A/2B deletions." (PMID 40548109, 2025). "We found that cyclin-dependent kinase inhibitor 2A (CDKN2A) had the highest mutation frequency and was significantly down-regulated in tumor samples." (PMID 39897130, 2025). "Asian patients with PDAC had fewer CDKN2A mutations, a genotype linked to improved survival and reduced tumor aggressiveness." (PMID 41187942, 2025). "This study reports the spatially separate regions of LM‐BN and LMS in different tumor development stages characterized by their different transcriptomic and gene mutation patterns, such as CDKN2A/B loss in LMS." (PMID 39691991, 2025). "A third subclone emerged during relapse, acquiring additional mutations (IGHV and CDKN2A) and amplifications (chr5q and chr7) and became the dominant clone in the relapsed intestine tumor." (PMID 40876452, 2025). "We confirmed that group 2 lost the expression of all 9p21-encoded proteins in the tumor, whereas group 4 lost CDKN2A only compared to 9p21 wild-type EACs." (PMID 39753721, 2025). "CDKN2A encodes two potent tumor suppressor proteins, p16 and ARF, making it a powerful tumor-suppressing locus." (PMID 40723291, 2025). "Genome-wide association studies have identified a locus near the tumor suppressor CDKN2A to be associated with susceptibility to HS in BMD." (PMID 40149290, 2025). "In Cluster 1, 94% of patients exhibit LOH 9/9p, closely associated with the complete deletion of CDKN2A, a key tumor suppressor gene that regulates the cell cycle." (PMID 40805197, 2025).
tumor (continued). "Deletion of the p16INK4a protein encoded by CDKN2A leads to an uncontrolled cell cycle, which promotes tumor cell proliferation." (PMID 40703518, 2025). "Six tumours (5.9%) had a CDKN2A mutation, three of which were in patients with the germline p16-Leiden mutation." (PMID 40107205, 2025). "(C) Percent of missense somatic mutations in CDKN2A that were classified as functionally deleterious (black box), indeterminate function (gray box), or functionally neutral (white box) group by tumor type." (PMID 40238651, 2025). "An assessment of the impact on survival of BRAF V600E mutational status in the context of CDKN2A deletions and tumor location was performed." (PMID 40860828, 2025). "High-risk homozygous CDKN2A/B deletions were identified in one grade 3 tumor, with hemizygous deletions, unexpectedly, in three grade 2 tumors." (PMID 40951339, 2025). "Further analysis with ISH on CDKN2A was performed on 16 variants with sufficient sample quantity and tumor cell content." (PMID 40796116, 2025). "CDKN2A/B homozygous loss was found in one grade 3 NF2-mutated tumor, while hemizygous loss was detected in three grade 2 cases." (PMID 40951339, 2025). "Mutations or deletions in the CDKN2A gene can result in the loss or reduction of p16INK4a function, leading to aberrant activation of the cell cycle and promoting tumor initiation and progression." (PMID 41340127, 2025). "Over half of HCC cases exhibit somatic tumor inactivation of cyclin-dependent kinase inhibitor 2A (CDKN2A), the gene that encodes p16INK4A and p14ARF proteins, owing to epigenetic silencing, loss-of-function mutations or chromosomal deletion." (PMID 39780710, 2025). "Another critical gene impacted by CTRP6 mutations is CDKN2A (p16), which functions as a tumor suppressor by regulating cyclin-dependent kinases to prevent uncontrolled cell division and inhibit cell proliferation." (PMID 39979869, 2025). "The significance of CDKN2A/B loss on overall survival was consistently corroborated by internal validation and within tumor grades." (PMID 39584448, 2025). "Conditional deletion of Cdkn2a, which encodes the frequently inactivated tumor suppressors p16INK4a and p19ARF, in KrasG12D mice enhances PanIN progression and invasive cancer development." (PMID 40829173, 2025). "The right temporal lobe tumor exhibited EGFR amplification and homozygous deletion of CDKN2A/B, and genetic changes have often been linked to more aggressive tumor behavior." (PMID 41473634, 2025). "Aberrant DNA methylation, such as the hypermethylation of tumor‐suppressor gene promoters (e.g., CDKN2A, RASSF1A), is a well‐recognized hallmark of cancer." (PMID 40959208, 2025). "Tumor regions expressing CDKN2A exhibit distinct infiltration of SPP1(+) tumor-associated macrophages (TAMs), MMP7 enrichment, and unique signaling interactions with adjacent regions." (PMID 40406488, 2025). "Unusually, the CDKN2A (cyclin-dependent kinase inhibitor 2A) gene encodes two unrelated proteins with independent tumour suppressor functions, p14 ARF and p16 INK4A." (PMID 40723241, 2025).